TNF (tumor necrosis factor)
Diseases named in the same sentence as TNF in open-access papers (continued):
Sharing a sentence is not in itself a finding about the gene and the disease.
psoriasis (continued). "A descriptive analysis was performed of Individual Case Safety Reports (ICSRs) associated with an anti-TNF drug and related to the pregnant patients with psoriasis from 2009 and 2023, focusing our analysis on the specific pregnancy outcomes and fetal/neonatal disorders." (PMID 39065754, 2024). "Moreover, TNF-α acts with IL-17A, co-regulating cytokines and keratinocyte genes associated with psoriasis and influencing keratinocyte function." (PMID 39311381, 2024). "The shift from broad immunosuppression (via TNF-α inhibitors) to more specific immune modulation with ustekinumab may help avoid further exacerbations of paradoxical psoriasis while effectively controlling the underlying condition." (PMID 39927272, 2024). "Numerous paradoxical reactions have arisen during targeted therapy for psoriasis and atopic dermatitis, including the emergence of anti-nuclear antibodies (ANAs) and anti-dsDNA antibodies caused by TNF-α inhibitors in certain patients, resulting in autoimmunity." (PMID 39618670, 2024). "Additionally, the successful treatment of psoriasis with biologics such as tumor necrosis factor inhibitors or interleukin 12/23 inhibitors is associated with a significant reduction in depression symptoms." (PMID 39201033, 2024). "Furthermore, KCs stimulated by a combination of psoriasis-associated cytokines (TNF-α, IL-1A, IL-17A, IL-22, and oncostatin M) activate autophagic flux, which leads to recurrent psoriasis inflammation and increased skin barrier damage." (PMID 38606161, 2024). "Evaluation of the NLRP3 gene polymorphism, the serum level of CRP and TNFα in psoriasis patients and assessment of the NLRP3 (rs10754558) gene polymorphism, CRP and TNFα with disease severity and their role as biomarkers for response to Methotrexate and Adalimumab in psoriasis." (PMID 38965465, 2024). "Over the past few years, several studies have reported that targeted therapies against psoriasis cause eczematous damage, specifically the anti-tumor necrosis factor alpha (TNF-α) and anti-interleukin 17 (IL-17) therapies with ustekinumab, secukinumab, ixekizumab, etc. targeted therapeutic agents." (PMID 39777333, 2024). "The underlying mechanism involves genetic predisposition (HLA-Cw6 is strongly associated with early onset severe psoriasis) and a dysregulation of certain immunological pathways, particularly the TNF/IL-23/IL-17 axis that has been shown to play a crucial role in the development of psoriatic lesions." (PMID 39000125, 2024). "These proteins contribute to essential biological functions associated with the pathological features of psoriasis, including the tumor necrosis factor-mediated signaling pathway, cytoplasmic sequestering of NF-κB, and the cellular response to lipopolysaccharide." (PMID 39590306, 2024). "Tumor Necrosis Factor α (TNFα), a proinflammatory cytokine regulating the NF-κB pathway activity, has been associated with numerous autoimmune diseases such as Crohn’s disease (CD) and psoriasis (PsO)." (PMID 36833372, 2023). "A lower elimination rate, in addition to its higher initial dosage, may help to explain its higher risk of psoriasis AEs, even among the TNF inhibitor cohorts, given that TNF inhibition is correlated with psoriasis." (PMID 37369753, 2023). "Furthermore, we used a psoriasis-associated cytokine mixture (Pso Mix) (IL-17, TNF-α, IL-1α, OSM and IL-22) to stimulate primary KCs to mimic the psoriatic profile." (PMID 37497003, 2023). "Various cytokines and adhesion molecules, including interleukin (IL)-1, IL-2, IL-6, IL-8, IL-12, IL-18, TNF-α, and nerve growth factor, are abnormally expressed in the lesions of psoriasis patients, suggesting that psoriasis is associated with the release of NF-κB-regulated inflammatory cytokines." (PMID 36835162, 2023). "Suppression of circulating psoriasis pathogenic molecules, including IL-17 cytokine family and TNF." (PMID 37108251, 2023).
psoriasis (continued). "TNF-α is another key proinflammatory cytokine that promotes immune cell migration towards the skin resulting in keratinocyte proliferation, which is one of the hallmark manifestations of psoriasis." (PMID 37546687, 2023). "All of the TNF inhibitor therapies approved for the treatment of RA and three out of the four non-TNF inhibitor drugs studied had a statistically significant association with psoriasis when compared to methotrexate." (PMID 37369753, 2023). "Therefore, some experts believe that TNF-α inhibitors are the systemic drugs of choice for the treatment of psoriasis patients with cardiovascular risk factors." (PMID 38149053, 2023). "All of the non-TNF inhibitor monotherapy cohorts, except tofacitinib, were significantly associated with psoriasis when compared to methotrexate: tocilizumab ROR 5.31 and 95% CI [2.32–12.12], abatacept 4.63 [2.07–10.34], rituximab 3.83 [1.48–9.88], and tofacitinib 1.97 [0.85–4.58]." (PMID 37369753, 2023). "Another research hotspot, TNF-α, is one of the key pathogenic factors of psoriasis." (PMID 36837593, 2023). "Furthermore, genetic polymorphisms of TLRs, IL-1β, LY96, and TIRAP have been associated with a response to anti-TNFα or ustekinumab in psoriasis." (PMID 37511413, 2023). "In a Spanish study that included 20 patients with psoriasis and psoriatic arthritis, both the AA-rs6920220 and the AC/CC-rs610604 genotypes were associated with a greater quality of life improvement after anti-TNF-α." (PMID 37372997, 2023). "In particular, the HLA-C rs12191877 polymorphism was associated with the response to anti-TNF drugs (a reduction of 75% in psoriasis area and severity index score [PASI 75] at 3 months) in 144 white patients (from Spain) (OR = 0.30, 95% CI = 0.11–0.88, p = 0.027)." (PMID 37240048, 2023). "In psoriasis, uncontrolled keratinocyte proliferation is associated with activation of the mTOR pathway and involves different Th-1, Th-17, and Th-22 immune cells, and their effector cytokines (e.g., IL-1β, IL-6, IL-17A, TNF-α) that act on keratinocytes." (PMID 37371141, 2023). "IFX and ADA are the most frequently associated with psoriasis among anti-TNF drugs." (PMID 37175894, 2023). "In this study, we analyzed over 880 thousand postmarketing safety reports from patients being treated for RA with a single therapeutic and provided evidence for a statistically significant association of psoriasis adverse events with TNF inhibitor use as compared to methotrexate." (PMID 37369753, 2023). "Furthermore, we quantified the difference in the reported risk of developing psoriasis in RA patients between the TNF inhibitor cohorts." (PMID 37369753, 2023). "Given the results of the United Kingdom study showing that incidence of tuberculosis varies with the severity of psoriasis, immune status including TNF-α and IL-17 -induced inflammation may affect the MDR-TB risk." (PMID 37035321, 2023). "Whereas the TNFα–IL-23–Th17 axis plays a central role in T cell-mediated plaque psoriasis, the innate immune system appears to have a more prominent role in the pustular variants of psoriasis." (PMID 38139369, 2023). "Psoriasis, which is characterized by hyper-proliferative keratinocytes and auto-reactive immune cells, was associated with low serum levels of H2S and high IL-6, IL-8, and TNFα." (PMID 36768979, 2023). "Further research may provide a more detailed underlying immunological mechanism of paradoxical psoriasis and help target those individuals’ pre-initiation of TNF-inhibition who may have a predilection to develop paradoxical psoriasis." (PMID 37664349, 2023). "In psoriasis, dendritic cells produce an increased amount of TNFα, which may be caused by the increased generation of ROS, as in vitro studies have shown that oxidative stress increases the production of IL-8 and TNFα by dendritic cells." (PMID 36292991, 2022).
psoriasis (continued). "Furthermore, TLR2 variants (e.g., rs4696480 and rs11938228) have been shown to be associated with the response to anti-TNF treatment in patients with psoriasis." (PMID 35517818, 2022). "Moreover, TNF-α, as the homotrimer cytokine, is associated with altering the cell cycle, especially in keratinocytes and hair follicles in psoriasis." (PMID 35203707, 2022). "Therefore, the association identified in 20q13 has further implicated the link between platelets activity and anti-TNF-α treatment response in psoriasis." (PMID 36059983, 2022). "However, using TNF inhibitors increases the risk of paradoxical psoriasis occurrence by approximately 1.915 times that of non-TNF inhibitor users." (PMID 36430392, 2022). "Furthermore, the polymorphism in the promoter region of the TNF-alpha gene, previously established in psoriasis, was also found in patients with chronic obstructive pulmonary disease." (PMID 35163689, 2022). "The mechanism underlying psoriasis and chronic inflammatory diseases such as atherosclerosis has been explained by the involvement of T-cell activation and/or inflammatory cytokines such as tumor necrosis factor-α (TNF-α), interleukin (IL)-17, and IL-23." (PMID 36555497, 2022). "An international registry of autoimmune diseases induced by biologics (the BIOGEAS registry), which included 12,731 patients, demonstrated that psoriasis was the most frequently induced autoimmune disorder (6375 cases), and 99% of cases were caused by TNF-α inhibitors." (PMID 35884790, 2022). "Finally, disease-specific cellular and molecular events in psoriasis are directly linked to the TNF–IL-23–Th17 inflammatory pathway." (PMID 35883760, 2022). "Accumulative evidence indicates that regulatory T cells (Tregs) play a key role in psoriasis pathogenesis and that Treg dysfunction causes an aberrant release of proinflammatory cytokines, including tumor necrosis factor (TNF)-α, IL-6, IL-17, and IL-23, and activates NF-κB signaling." (PMID 35629363, 2022). "This phenomenon may be associated with the inhibition of TNFα production at different stages of psoriasis development, including NET creation." (PMID 35886575, 2022). "Antioxidants may suppress secretion of TNF-α, while their deficiency may be a potential risk factor for the development of psoriasis." (PMID 36421647, 2022). "Considering the high efficacy in psoriasis therapy of TNF-α inhibitors, it is likely that these SNP-associated genes could be involved in the response of immunotherapy in psoriasis." (PMID 36059983, 2022). "Moreover, anti-TNF-α is therapy probably associated with normalization of NADPH oxidase activity in psoriasis patients." (PMID 35321240, 2022). "Furthermore, rs4819554 was significantly associated with the response to anti-TNF drugs in psoriasis patients." (PMID 35372081, 2022). "Another large study, a retrospective analysis, was conducted on 56 million adults, including 309,660 subjects with psoriasis, to find out whether anti-TNFα agents affect the risk of AD development." (PMID 36226313, 2022). "Tumor Necrosis Factor (TNF) inhibitors decreased the risk of AD in patients with psoriasis." (PMID 35457278, 2022). "However, no comprehensive meta-analysis investigating the incidence estimates and risk factors for anti-TNF-induced psoriasis is currently available." (PMID 35300336, 2022). "Psoriasis is classified as an autoimmune disease caused by malfunctioning pathways and elements of the immune system T cells, dendritic cells, cytokines such as interleukin-23, interleukin-17, and tumor necrosis factor." (PMID 35163855, 2022). "Nonetheless, psoriasis is, indeed, caused by the chaos of triggered immune cells and its cytokines, such as tumor necrosis factor (TNF)-α, interleukin (IL)-17, IL-22, IL-23, and granulocyte–macrophage colony-stimulating factor (GM-CFS) that flare up throughout the pathway." (PMID 35203707, 2022).
psoriasis (continued). "Over the last two decades, significant advances in understanding the pathogenic mechanisms underpinning psoriasis, have led to the adoption of biological treatments (“biologics”) targeting the key cytokines TNF, IL-23 and IL-17A, which have transformed disease management." (PMID 34362923, 2021). "The influence of IL-12/23 inhibitors on cardiovascular safety was also compared with those of other biologics approved for the treatment of psoriasis in some trials, which reported a comparable risk of MACEs among ustekinumab, TNF-α inhibitors, and IL-17 inhibitors." (PMID 34803716, 2021). "Whether the risk of heart failure reduces or increases in psoriasis patients treated with TNF-α inhibitors has been discussed for a long time." (PMID 34803716, 2021). "Currently, T cells and dendritic cells are considered as the primary immune cells that release cytokines associated with psoriasis, such as interleukin (IL)-17A, IL-22, tumor necrosis factor (TNF)-α, and interferon (IFN)-γ, which affect keratinocyte proliferation." (PMID 34955833, 2021). "We examined whether the key cytokines (TNFα, IL-22, IL-1β, IL-17A) implicated in the pathogenesis of psoriasis modulate the circadian oscillation of the clock genes in HaCaT keratinocytes." (PMID 35008548, 2021). "In addition, selenium deficiency, often observed in patients, can be a risk factor for the development of psoriasis, and supplementation of this element suppresses secretion of TNF-α." (PMID 35010995, 2021). "In addition to the psychological stress caused by psoriasis, it has been reported that inflammatory cytokines are related to mood disorders, including elevated levels of cytokines, including TNF-a, IL-6 and IL-1." (PMID 34372872, 2021). "However, there are no relevant research results on the risk of infection of SARS-CoV-2 for patients with psoriasis with anti-TNF-α therapy." (PMID 34938746, 2021). "Recently, a much higher incidence of psoriasis of up to 10.5% has been described in a retrospective analysis; in the same study, female gender, foregut disease location, and fistulizing and stricturing disease appeared to be risk factors for anti-TNFα-induced psoriasis." (PMID 33477990, 2021). "Our finding that Reg-3 regulates levels of TNF, a cytokine strongly implicated in development of psoriasis flares, suggested that Reg-3 might play a controlling role in the development/severity of this disease." (PMID 34298932, 2021). "A large retrospective US study with information from over 7.5 million patients with a mean follow-up time of 4.7 years found individuals with psoriasis who received TNF-α inhibitors had a lower risk for major cardiovascular events than those receiving oral/phototherapy or topical therapy." (PMID 34829740, 2021). "However, despite the ability of psoriasis-associated TNF and IL-17 to reduce KIT expression in melanocytes, the number of melanocytes in psoriasis lesional skin is increased." (PMID 34884858, 2021). "Interestingly, targeted (and also systemic) therapy use (TNF-α inhibitors, IL-17 inhibitors, IL-23 inhibitors, and apremilast) was inversely associated with worsening psoriasis, with an estimated odds ratio (OR) of 0.49." (PMID 34945136, 2021). "Thus, TNF blocking carries a risk of inhibiting the activity of some suppressor cells, and we sometimes encounter exacerbation of autoimmune diseases such as psoriasis, lupus-like syndrome, multiple sclerosis, and sarcoidosis during anti-TNF treatment." (PMID 34681582, 2021). "Proper control of psoriasis provided by TNF-α inhibitors may contribute to decreased risk of cardiovascular diseases in treated patients." (PMID 33927259, 2021). "Furthermore, TNF-α works in part by enhancing the elevated level of active, phosphorylated NF-κB, a key transcription factor implicated in the development of psoriasis." (PMID 34679744, 2021).
psoriasis (continued). "Nearly 2-5% of patients with Crohn's disease and RA receiving anti-TNF-α mAbs (infliximab, adalimumab and etanercept) were associated with an increased risk of paradoxical psoriasis due to prolonged type I interferon production by immature plasmacytoid dendritic cells (pDCs) in the dermis 10,12." (PMID 33859756, 2021). "TNF is also closely associated with the pathogenesis of psoriasis." (PMID 34367173, 2021). "Moreover, psoriasis has been associated with increased inflammatory cytokines, in which the IL-23/Th17 axis with TNF-α, IL-21, and IL-22 play a role in the control of inflammation." (PMID 34722590, 2021). "Interestingly, pro-inflammatory cytokines associated with psoriasis such as TNF, IL-17 and IL-6 suppress melanin synthesis, but others can also activate the process." (PMID 34884858, 2021). "TNF-α dysfunction can cause many diseases, such as RA, psoriasis, and ankylosing spondylitis." (PMID 34093213, 2021). "Hence, in psoriasis patients with cardiovascular risk, the proactive use of TNF-α inhibitors appears to be warranted." (PMID 34441936, 2021). "Specifically, CD8 T-cells; CD4+ Th17 cells, responsible for producing IL-17 and IL-22; type 3 innate lymphoid cells, responsible for producing IL-17 and IL-22; and γδ T cells, responsible for producing IL-17 and TNF- α, are implicated in the pathogenesis of psoriasis." (PMID 34884596, 2021). "In addition, Reg-3 was found to be the only family member which regulates transcript levels of TNF, a cytokine implicated in chronic inflammatory diseases including psoriasis." (PMID 34298932, 2021). "TNF-α and IL-12 are important pathogenic factors in the development of psoriasis." (PMID 34572503, 2021). "The TNF-α/IL-23/IL-17 axis is integral in the underlying pathogenesis of psoriasis." (PMID 34884596, 2021). "Furthermore, the association between IL23R polymorphisms and the risk of developing toxicity and/or paradoxical psoriasis due to the anti-TNF medication has been demonstrated in a study with Spanish patients (n = 161)." (PMID 33921427, 2021). "In addition, TNFAIP3 gene polymorphisms were associated with responses to TNF antagonists in psoriasis." (PMID 32280718, 2020). "Lower risk for AD also was seen in psoriasis patients treated with a TNF blocking agent." (PMID 32203525, 2020). "Although the underlying mechanism of psoriasis remains unclear, recent studies have revealed some predominant pathways underlying pathological conditions, as well as the contribution of the TNF/IL-23/IL-17 axis." (PMID 33613558, 2020). "Individuals undergoing successful anti-TNFα (adalimumab) treatment for psoriasis had a reduction in the number of pathogenic NKp44+ ILC3s and an increase in NKp44– ILC3s in the circulation, suggesting that a major role of TNFα in the pathogenesis of psoriasis includes potentiating pathogenic ILC3s." (PMID 32153574, 2020). "Recent studies published by Wolk and Kiluk and colleagues point out that this type of tissue releases molecules directly associated with interplay between CMS and psoriasis: TNF-α (Tumor necrosis factor α), IL-6 (interleukin 6), leptin, resistin, vaspin, and omentin." (PMID 32456228, 2020). "Notably, numerous diseases that benefit from TNF-α inhibitor therapy are associated with an inherent increased risk of classical psoriasis." (PMID 33114187, 2020). "Furthermore, normal human keratinocytes show increased expression of IL-1 group mRNA after treatment with psoriasis-associated cytokines (TNFα, IL-1α, IL-17,IL-22)." (PMID 32484435, 2020). "Finally, we demonstrate that the product of the plasma levels of IFNγ and TNFα associate with the presence of early coronary artery disease burden in patients with psoriasis." (PMID 32646751, 2020).